IL6 (interleukin 6)
Diseases named in the same sentence as IL6 in open-access papers (continued):
Sharing a sentence is not in itself a finding about the gene and the disease.
Insulin resistance (continued). "The uniqueness of our results is in the identification of a consistent association between 4-HNE, IL-6 and insulin resistance (i.e., HOMA-IR), which suggests the existence of a mechanistic link between these molecules and the development of insulin resistance during exposure to hypoxia." (PMID 24733551, 2014). "Expression of adipose IL-6 positively correlates with insulin resistance both in vivo and in vitro." (PMID 24733068, 2014). "In addition, one previous study has shown that IL-6 correlated positively with BMI and with measures of insulin resistance in abdominal obese male subjects." (PMID 24741576, 2014). "Moreover, hsCRP and IL-1β and TNF-α and IL-6 positively correlated with insulin resistance (P < 0.05)." (PMID 24795503, 2014). "IL-6 is hypothesized to sensitize the liver to injury, stimulate hepatocyte apoptosis, induce insulin resistance, and participate in NASH development." (PMID 24466347, 2014). "Besides the direct effects of inflammatory cytokines on lipogenesis and fibrogenesis, MCP-1, TNF-α, and IL-1β, IL-6 can induce insulin resistance." (PMID 25136608, 2014). "IL-6 is secreted by enlarged, activated adipocytes which may result in a systemic elevation of IL-6 plasma levels leading to insulin resistance." (PMID 24733551, 2014). "Dysregulation of adipokines originating from visceral adipose tissue, such as tumor necrosis factor-α (TNF-α), interleukin-6 (IL-6), leptin, and adiponectin, has been reported to influence insulin resistance and growth hormone (GH) secretion, which are closely associated with sarcopenia." (PMID 25517117, 2014). "IL-6 participates in the development of insulin resistance via different mechanisms." (PMID 24387137, 2014). "Moreover, it has been previously shown how an excess of IL-6 can also induce insulin resistance in hepatocytes, adipocytes, and skeletal muscle." (PMID 25514415, 2014). "Additionally, TNF-α has been demonstrated to be the most significant predictor of pregnancy-induced insulin resistance and be more highly synthesized and released from the placenta compared with IL-6 or IL-8." (PMID 25202741, 2014). "It is speculated that increased insulin resistance and increase in other adipokines such as IL-6 may contribute to the decreased serum levels of adiponectin in patients with both CAD and T2DM." (PMID 24719717, 2014). "Interestingly, the inflammatory cytokines IL-1β, TNF-a, and IL-6 expression increased significantly and induced insulin resistance in the HFD-Nrf2-null group, compared with the HFD-WT group." (PMID 24188280, 2013). "Moreover, ablation of progranulin prevented mice from high fat diet-induced insulin resistance and blocked elevation of an inflammatory cytokine, interleukin-6 (IL-6), in adipose tissue." (PMID 23409033, 2013). "CRP plays a role in inflammation and insulin resistance and may be derived from adipose tissue or elevated as a consequence of higher IL-6 and MCP-1 levels." (PMID 24227909, 2013). "Recently, a report shows that PGRN could induce insulin resistance through stimulating IL-6 expression in adipocytes." (PMID 23476101, 2013). "In addition, several studies have elucidated increased IL-6 levels in obese patients correlated with insulin resistance and the incidence of diabetes." (PMID 24023413, 2013). "In particular, the induction of SOCS3 in liver may be an important mechanism of IL-6-mediated insulin resistance." (PMID 23861927, 2013). "TNF-α and IL-6 are involved in the development of insulin resistance and atherogenic processes." (PMID 24027356, 2013). "To assess the effects of BM on the increased local inflammatory levels in DIO mice, we measured the mRNA expression levels of several important pro-inflammatory cytokines involved in fat deposition and insulin resistance, including Mcp-1, Il-6 and Tnf-α in EAT, SAT and BAT." (PMID 24358329, 2013).
Insulin resistance (continued). "Hence, this relation between IL6 and insulin resistance should be extended to propose a central role of HMGB1 in insulin resistance through it action on IL6 secretion." (PMID 24073286, 2013). "It has also been shown a strong link between IL-6 serum levels and insulin resistance." (PMID 24073286, 2013). "The proinflammatory effects of resistin were attributed to its ability to activate NF-kB signaling pathway and subsequently increase the production of proinflammatory cytokines including TNF-α and IL-6, both of which can impair insulin signaling pathways and lead to insulin resistance." (PMID 23772224, 2013). "A novel observation amongst models of fetal overnutrition is that the female offspring showed a raised serum IL-6 concentration as young animals compared to controls, and a reduction in resistin, implicating these adipokines in development of insulin resistance." (PMID 23423541, 2013). "Furthermore, IL6 is a key factor in the onset and progression of NASH and in the development of insulin resistance, while a relative deficiency of IL10 can be associated with NASH." (PMID 24084730, 2013). "Recently IL-6 has been shown to contribute to systemic insulin resistance." (PMID 23819063, 2013). "Inflammatory mediators such as TNF-α and IL-6 either alone or through synergistic effect could lead to the development of insulin resistance by blocking the signal transduction of insulin, impairing insulin sensitivity, and increasing free fatty acids." (PMID 23840093, 2013). "Insulin resistance is associated with a state of chronic low-grade inflammation, and mediators such as tumor necrosis factor-α (TNF-α), interleukin 1beta (IL-1β), and interleukin-6 (IL-6) have been identified as being involved in metabolic control and impairment in insulin-receptor signaling." (PMID 22927832, 2012). "In addition to differences in the levels of adiponectin, the levels of interleukin 6 (IL-6), which promotes insulin resistance, are reduced in both epididymal and perinephric fat of GHR-KO as compared to normal mice." (PMID 23248643, 2012). "It is therefore plausible that increased IL-6 expression in adipose tissue after envenomation may be due to TNF-α production, suggesting that TNF-α and IL-1β work in concert to cause insulin resistance." (PMID 22816003, 2012). "Lastly, the greater insulin resistance in IL-6 deficient mice fed a HFD is not explained by differences in adipose tissue mitochondrial content." (PMID 23240005, 2012). "They interfere with adipocyte function through the production of pro-inflammatory cytokines such as TNF-α, IL-1β and IL-6, which can lead to insulin resistance, modify adipokine secretion and lead to an excess of free fatty acid secretion through increased lipolysis and diminished lipogenesis." (PMID 23201837, 2012). "Inflammatory cytokines such as TNF-α and IL-6 are known to promote insulin resistance." (PMID 21826136, 2012). "Although not a universal finding, IL-6−/− mice have been shown to develop age-associated insulin resistance and when fed a HFD become markedly more insulin resistant than WT controls." (PMID 23240005, 2012). "The specific role of IL-6 in the pathogenesis of insulin resistance is still controversial." (PMID 22272193, 2012). "The SOCS3 connection between IL-6 and insulin signaling could be an explanation to the observation that mice, when infused with high doses of IL-6 (0.5 μg/h), induced insulin resistance in skeletal muscle." (PMID 22761857, 2012). "The role of IL-6 in insulin resistance in humans thus remains to be resolved." (PMID 22615828, 2012). "Inflammation and insulin resistance are closely linked and inflammatory cytokines such as tumor necrosis factor (TNF), interleukin (IL)-6, IL-1 and IL-8 may inhibit insulin signaling by multiple mechanisms." (PMID 22691241, 2012).
Insulin resistance (continued). "Pro-inflammatory cytokines: TNF-α, IL-6 and IL-1β are synthesized by numerous tissues, including obese adipose tissue, which, in addition to their well described pro-inflammatory properties, are involved in the genesis of insulin resistance." (PMID 23201837, 2012). "The purpose of this study was to determine whether levels of interleukin-6 (IL-6) in childhood are related to insulin resistance in adolescence." (PMID 22272193, 2012). "Furthermore, TLR2, following ligation with specific ligands, can activate signal transduction, promote interleukin (IL)-6 production, and mediate initial events related to fatty acid-induced insulin resistance in muscle." (PMID 23213270, 2012). "For example, adipose tissue insulin resistance in rats fed with a glutamine-supplemented diet is accompanied by reduced TNFα and interleukin-6 levels, as well as augmented adiponectin levels, which seem to be the cause of increased insulin sensitivity in other organs." (PMID 23024762, 2012). "The role of IL-6 in insulin resistance has been controversial and sometimes paradoxical." (PMID 23028874, 2012). "Interleukin-6 (IL-6) is considered to be the major mediator of the hepatic acute-phase reaction and is thought to play a central role in the pathogenesis of cardiovascular disease in patients with insulin resistance." (PMID 21822486, 2012). "However, as hepatic and adipose production of IL-6 promote insulin resistance, IL-6 produced by skeletal muscle especially during intense exercise is beneficial." (PMID 23028874, 2012). "Moreover, pro-inflammatory adipokines, such as tumor necrosis factor- α (TNF-α) and IL-6 lead to the development of insulin resistance." (PMID 21569357, 2011). "Insulin resistance induces high expression of IL-6 and TNF-α mRNA in epididymal adipose tissue." (PMID 22144985, 2011). "The results obtained suggest that an altered milieu due to insulin resistance may influence production of IL-6 in these cells." (PMID 21547256, 2011). "Furthermore, the degree of insulin resistance, glucose intolerance, liver steatosis, and adipose and liver inflammatory marker expression (TNFα, IL-6, IL-10, IFN-γ, MCP-1, MIP1α) induced by high fat feeding in CD1d−/− were not different from WT." (PMID 21674035, 2011). "All these clinical and experimental observations suggest that TNF-α and IL-6 may be involved in the pathogenesis of insulin resistance, and there is a positive correlation between insulin resistance and inflammation in GDM and macrosomia." (PMID 22144985, 2011). "Furthermore, IL-6 has been shown to be one of the mediators of hyperinsulinemic state, 10%−35% of the body's basal circulating IL-6 is derived from adipose tissue, and a positive correlation has been found between insulin resistance and circulating IL-6." (PMID 22144985, 2011). "In analogy, the elevated IL-6 levels in our septic and morbidly obese patients may contribute to insulin resistance." (PMID 20825686, 2010). "Also, inflammatory cytokines including tumor necrosis factor and interleukin 6 are proposed in pathogenesis of hepatocellular injury in insulin resistance/MetS." (PMID 21047423, 2010). "We have examined whether saturated nonesterified fatty acids (NEFA) and insulin, which increase in concentration with developing insulin resistance, can trigger the production of interleukin (IL)-6 and tumor necrosis factor (TNF)-α in human monocytes." (PMID 21054880, 2010). "High circulating levels of TNF-α, IL-6, and leptin are recognized as markers of insulin resistance." (PMID 21403905, 2010). "It has been suggested that insulin resistance, through both the activation of nuclear factor kappa B by increased levels of cytokines (i.e., IL-6 and TNF-alpha) and the releasing of free fatty acids by excess adipose tissue, is involved in the pathogenic mechanisms leading to SAHS in humans." (PMID 19262746, 2009). "An ongoing debate considers the relevance of IL6 as a mediator of insulin resistance in humans." (PMID 19087258, 2008).
Insulin resistance (continued). "• Insulin resistance is further predicted by IL6, leptin and adiponectin." (PMID 19087258, 2008). "Resistin and other molecules commonly called adipokines, such as TNF-α, IL-6, and visfatin,are produced and secreted by both adipocytes and macrophages, and have beensuggested to be important players in the pathogenesis of insulin resistance andatherosclerosis." (PMID 19125180, 2008). "Among them, IL-6 has the strongest correlation with insulin resistance and type II diabetes." (PMID 19787081, 2008). "On the other hand, the role of IL-6 in insulin resistance isalso controversial." (PMID 18604303, 2008). "The role of IL-6 in insulin resistance remains controversial." (PMID 19936194, 2008). "According to a unifying hypothesis, HSV-1, CMV, H. pylori and Chlamydia pneumoniae induce production of proinflammatory cytokines, such as TNF-alpha and IL-6 which are leading to chronic subclinical inflammation, insulin resistance and the metabolic syndrome." (PMID 17140429, 2006). "Moreover, IL-6 leads to insulin resistance in vivo when chronically administered to mice at levels that are similar to those found in obese individuals." (PMID 16787541, 2006). "Interestingly, the peak in TNFα and IL-6 levels after LPS administration to humans precedes a phase of prolonged insulin resistance that begins approximately 6 h after LPS administration, closely approximating the time course of resistin induction." (PMID 15578112, 2004). "Additionally, the overproduction of IL-6 in adipose tissue macrophages may worsen insulin resistance and encourage hepatic gluconeogenesis." (PMID 40002771, 2025). "The pro-inflammatory cytokine interleukin-6 (IL-6) released from macrophages and adipocytes regulates differentiation, migration, proliferation, and cell death to create inflammation, which in turn significantly contributes to the pathophysiology of type II diabetes mellitus and insulin resistance." (PMID 39817379, 2025). "Furthermore, adipocyte‐specific IL‐6 deficiency did not markedly affect systemic insulin resistance in mice fed HFD." (PMID 40781882, 2025). "As the primary mediators, the inflammatory factors TNF-α and IL-6 cooperated with other factors to inhibit or damage insulin secretion by pancreatic islet beta cells and simultaneously reduce the activity of insulin receptors, thus leading to insulin resistance." (PMID 40842498, 2025). "Individuals with metabolic features such as central adiposity or insulin resistance may be evaluated using IL-6/TNF panel testing, whereas those with autoimmune features, such as photosensitivity, anti-dsDNA positivity, or low complement, may be tested using an ISG/Type I interferon panel." (PMID 41440484, 2025). "Insulin resistance may contribute significantly to the development of MASLD and its induced abnormalities in lipid metabolism can lead to increased production of proinflammatory cytokines, such as TNF-α, IL-1b, and IL-6, as well as less adiponectin, thereby inducing systemic insulin resistance." (PMID 40567989, 2025). "Research has found a close association between low‐grade chronic inflammation and insulin resistance, suggesting that OS may contribute to this chronic inflammation, where inflammatory mediators such as TNF‐α and IL‐6 exacerbate the pathological state of insulin resistance." (PMID 40599237, 2025). "Interestingly, those expressions of “contractil genes” are associated to an increase of pro-inflammatory cytokines (TNFα, IL6 or IL1b) in insulin-resistance condition, while the presence of minoxidil or nebivolol reduces significantly the expressions of IL6 and IL1b." (PMID 41049496, 2025). "In mechanism level, LPS produced by gram-negative bacteria might lead to metabolic endotoxemia and LPS -dependent production of inflammatory cytokines, such as Interleukin-6 and Tumour Necrosis Factor-α that can contribute to development of insulin resistance and T2DM." (PMID 40406484, 2025).
Insulin resistance (continued). "The increased risk of developing diabetes in HCV infections is associated with insulin resistance and a chronic inflammatory response due to an increased synthesis of pro-inflammatory cytokines, mainly tumor necrosis factor (TNF) alpha and interleukin-6 (IL-6)." (PMID 39457712, 2024). "In obese individuals, an increase in circulating TNF-α due to an overall increase in fat tissue could lead to breast cancer tumorigenesis by contributing to insulin resistance and IL-6 synthesis regulation, considering that TNF-α was identified as a key regulator of IL-6 synthesis." (PMID 38247865, 2024). "In addition to TNF-α, IL-6 acts on adipose tissue to increase leptin secretion, suppress satiety, and increase adipose tissue lipolysis, which, in turn, promotes hepatic gluconeogenesis and hepatic insulin resistance." (PMID 39204094, 2024). "Furthermore, noradrenaline-stimulated IL-6 synthesis in adipocytes, and skeletal muscle-produced IL-6 may enhance lipolysis and gluconeogenesis and reduce insulin resistance." (PMID 38474057, 2024). "The promoting mechanism of TSH on insulin resistance may be due to its ability to induce the expression of a variety of inflammatory factors including interleukin-6 and tumor necrosis factor-α in adipocytes, and the inflammatory response can enhance islet resistance." (PMID 39525852, 2024). "Proinflammatory cytokines, such as tumor necrosis factor (TNF-α), interleukin-6 (IL-6), and nuclear factor B (NF-B), have been implicated in the activation of various intracellular inflammatory signaling pathways, including JNK and IKK, which can lead to glucose and insulin resistance." (PMID 38048013, 2024). "Additionally, IL-6 has been shown to impede the relaxation mediated by endothelium-dependent nitric oxide and augment contraction in an experimental model, indicating a direct involvement of IL-6 in microvascular dysfunction in the setting of insulin resistance." (PMID 38555461, 2024). "Similarly, IL-6 promotes hepatic glucose production and exacerbates insulin resistance." (PMID 39700087, 2024). "Similarly, a 5-week dietary intervention with mung bean peptide (245 mg/kg/day) in high-fat-diet-treated mice demonstrated notable improvements in insulin resistance, body weight, and several serum biomarkers including fasting blood glucose, C-peptide, IL-6, TNF-α, and MDA." (PMID 39203819, 2024). "Meanwhile, one previous study indicated that IL-6 could induce hepatic insulin resistance." (PMID 37113481, 2023). "Additionally, hesperidin demonstrated the ability to downregulate the expression of suppressor of cytokine signaling-3 (SOCS-3) and C-reactive protein (CRP) mRNA, both of which play pivotal roles in insulin resistance, and it also exhibited inhibitory effects on IL-6 production induced by LPS." (PMID 38234970, 2023). "Third, anxiety could promote the inflammatory response of patients, and some inflammatory factors, such as interleukin-6 (IL-6) and tumor necrosis factor-α (TNF-α), are risk factors for insulin resistance, which could contribute to insulin resistance, thereby promoting the prevalence of MetS." (PMID 36873213, 2023). "Moreover, the effects of IL-6 on diabetic renal injury may be due to increased insulin resistance and promotion of the inflammasome." (PMID 36776877, 2023). "The restoration of IRS-1 expression and the downregulation of insulin resistance markers highlight the potential of hesperidin as a promising therapeutic intervention to counter the negative impact of liver insulin resistance caused by IL-6." (PMID 38234970, 2023). "Moreover, one should consider the beneficial effects of some conventional drugs, such as methotrexate and hydroxychloroquine, on glucose metabolism as well as the various effects of bDMARDs, such as tumor necrosis factor, IL-6, or IL-1 antagonists, on insulin resistance." (PMID 36983150, 2023).